MYLIP (myosin regulatory light chain interacting protein)
Description:
Activity depends on E2 enzymes of the UBE2D family. Proteasomal degradation of MRLC leads to inhibit neurite outgrowth in presence of NGF by counteracting the stabilization of MRLC by saposin-like protein (CNPY2/MSAP) and reducing CNPY2-stimulated neurite outgrowth.
Synonyms: Idol; MIR
Tractability: Small molecule: it has a binding pocket of medium quality. Antibody: UniProt places it where antibodies can reach, with high confidence; its Gene Ontology location is reachable by antibodies, with medium confidence. PROTAC: UniProt records ubiquitination sites on it; ubiquitination databases record sites on it.
Gene: Protein-coding gene on chromosome 6 (16,129,086 to 16,151,367, forward strand). Ensembl gene ENSG00000007944.
Subcellular location: Cytoplasm; Cell membrane
Pathways (Reactome):
Immune System: Antigen processing: Ubiquitination & Proteasome degradation
Signal Transduction: NR1H2 & NR1H3 regulate gene expression to limit cholesterol uptake
Transport of small molecules: VLDLR internalisation and degradation
Gene Ontology:
Molecular function: cytoskeletal protein binding; protein binding; ubiquitin protein ligase activity; ubiquitin-protein transferase activity
Biological process: negative regulation of neuron projection development; nervous system development; protein ubiquitination; ubiquitin-dependent protein catabolic process; cholesterol homeostasis; negative regulation of low-density lipoprotein particle clearance; positive regulation of protein catabolic process; protein destabilization; regulation of low-density lipoprotein particle receptor catabolic process
Cellular component: cytosol; cytoplasm; plasma membrane
Genetic constraint (gnomAD): Loss-of-function variants: 26 observed, 45.89 expected, observed/expected ratio (o/e) 0.57, 90% interval 0.41 to 0.79. The upper end of that interval is the gene's LOEUF score, 0.79, which puts it in group 3 of 6, group 1 being the genes least tolerant of losing a copy. Missense variants: 494 observed, 569.91 expected, observed/expected ratio (o/e) 0.87, 90% interval 0.8 to 0.93. Synonymous variants: 213 observed, 223.72 expected, observed/expected ratio (o/e) 0.95, 90% interval 0.85 to 1.07.
Homologues: Orthologues: chimpanzee MYLIP (99% identical), macaque MYLIP (99% identical), dog MYLIP (96% identical), rat Mylip (96% identical), mouse Mylip (96% identical), pig MYLIP (96% identical), guinea pig MYLIP (94% identical), rabbit MYLIP (93% identical), tropical clawed frog mylip (82% identical), zebrafish mylipa (76% identical), zebrafish mylipb (64% identical), Drosophila melanogaster dnr1 (36% identical). Paralogues in human: EPB41L2 (27% identical), EPB41L4B (26% identical), EPB41L3 (26% identical), EPB41 (25% identical), EPB41L1 (24% identical), EPB41L5 (24% identical), FRMD3 (23% identical), EPB41L4A (22% identical), FRMD5 (21% identical), FRMD6 (15% identical).
Diseases named in the same sentence as MYLIP in open-access papers:
MYLIP is named in the same sentence as 40 diseases in open-access papers, as found by Europe PMC text mining. Sharing a sentence is not in itself a finding about the gene and the disease. The quoted sentences say what the papers report.
breast carcinoma (12 papers, 2017 to 2024). "The downregulation of MYLIP is associated with increased tumor migration and metastasis in breast cancer cells." (PMID 32899424, 2020). "In order to further evaluate the diagnostic values of TUSC8 and MYLIP in breast cancer, we used the receiver operating characteristic curve (ROC) analyses to assess the potential use of these two biomarkers for differentiation of breast cancer patients." (PMID 32039833, 2020). "Clinically, the receiver operating characteristic curve (ROC) analyses revealed that the combination usage of TUSC8 and MYLIP might become novel promising diagnostic biomarkers for breast cancer." (PMID 32039833, 2020). "Overexpression of miR-19b has been demonstrated to promote human breast cancer cell migration and metastasis by downregulating the myosin regulatory light chain interacting protein (MYLIP), involved in regulating cell movement and migration." (PMID 38954129, 2024). "According to the report, miR-190b was increased in breast cancer and was involved in proliferation, migration, and invasion of breast cancer cells by targeting MYLIP." (PMID 34490040, 2021). "We demonstrated that TUSC8 inhibited tumor growth and metastasis of breast cancer cells through sponging miR-190b-5p, leading to the down-regulation of MYLIP." (PMID 32039833, 2020). "Taken together, these results suggested that TUSC8 inhibited breast cancer growth and metastasis via miR-190b-5p/MYLIP axis, providing us new insights into developing potential therapeutic targets for breast cancer patients." (PMID 32039833, 2020). "Using RT-PCR assay in tumorous and adjacent normal breast tissues in 32 cases of breast cancer patients, we identified that TUSC8 and MYLIP were significantly down-regulated in breast cancer (p < 0.001)." (PMID 32039833, 2020). "In this case, in order to further investigate the upstream regulatory ceRNA network of MYLIP, we launched this study in breast cancer." (PMID 32039833, 2020). "In our previous studies, we revealed that inhibition of MYLIP facilitated the migration and metastasis of breast cancer cells, providing us a promising therapeutic target to interfere breast cancer development." (PMID 32039833, 2020). "To further validate the inverse correlation between hsa-miR-19b and MYLIP, we conducted the correlation analysis to test the expression levels of hsa-miR-19b and MYLIP in breast cancer samples at the same time." (PMID 28969074, 2017). "The data indicated that the expression of hsa-miR-19b was negatively correlated with MYLIP expression in breast cancer patient samples." (PMID 28969074, 2017). "In our research, we mainly explored the downstream effects of miR-19b and its target MYLIP in breast cancer metastasis from the aspects of cell adhesion molecules." (PMID 28969074, 2017). "We further explored that miR-19b was highly expressed and negatively correlated with MYLIP expression in breast cancer patient samples from the TCGA database." (PMID 28969074, 2017). "And the over-expression of miR-19b or inhibition of MYLIP facilitated the migration and metastasis of breast cancer cells, through conducting the wound healing assay and transwell invasion assay." (PMID 28969074, 2017). "MYLIP represents a potential marker and target for the diagnosis and treatment of breast cancer." (PMID 34631307, 2021). "Therefore, we constructed the ceRNA network of TUSC8, miR-190b-5p and MYLIP in breast cancer development." (PMID 32039833, 2020). "Finally, we found that miR-190b-5p was a more suitable candidate which showed the opposite expression pattern with both TUSC8 and MYLIP in breast cancer cells." (PMID 32039833, 2020). "Studies have confirmed that MYLIP inhibits the metastasis and progression of breast cancer." (PMID 32031203, 2020).
breast carcinoma (continued). "For the clinical relevance and diagnostic value in breast cancer patients, the ROC analyses indicated that the combination usage of TUSC8 and MYLIP might become novel promising biomarkers and targets for breast cancer diagnosis and treatment." (PMID 32039833, 2020). "Taken together, these findings comprehensively illustrate the regulatory mechanisms ofmiR-19b in breast cancer metastasis, and provide us new insights for exploring MYLIP and its related cell adhesion molecules as promising therapeutic targets to interfere breast cancer development." (PMID 28969074, 2017). "Additionally, we analyzed the expression level of MYLIP with the different status of breast cancer molecular classification markers (such as ER, PR and HER2)." (PMID 28969074, 2017). "Then we adopted the primary MYLIP mRNA expression data (log2) in breast cancer samples and adjacent normal breast tissues from the TCGA database, and found that the expression level of MYLIP was significantly down-regulated in breast cancer samples compared with normal breast tissues (***p < 0.001)." (PMID 28969074, 2017). "In this article, we mainly illustrated the regulatory mechanisms of miR-19b promoting breast cancer metastasis through directly targeting MYLIP expression and affecting the expression levels of cell adhesion molecules (including E-Cadherin, ICAM-1 and Integrin β1)." (PMID 28969074, 2017). "The high expression levels of MYLIP and E-Cadherin (CDH1) could significantly elevate the survival rates for breast cancer patients compared with their low expression groups (p = 0.0196 for MYLIP curve, p = 0.0070 for CDH1 curve)." (PMID 28969074, 2017). "Additionally, using the primary expression data of breast cancer patients from the TCGA database, we drew the overall survival curves for hsa-miR-19b, MYLIP and cell adhesion molecules (E-Cadherin, ICAM-1 and Integrin β1) respectively." (PMID 28969074, 2017). "We then explored whether TUSC8 regulates breast cancer metastasis via miR-190b-5p-MYLIP axis." (PMID 32039833, 2020). "The results indicated that over-expression of miR-19b and inhibition of MYLIP could significantly increase the relative invasive cell numbers compared with the control groups (*p < 0.05, **p < 0.01), which promotes the metastasis of breast cancer cells." (PMID 28969074, 2017). "The data showed that over-expression of miR-19b and inhibition of MYLIP could significantly reduce the relative gap distances at 48h compared with the control groups (*p < 0.05, **p < 0.01), which facilitates the migration capacities of breast cancer cells." (PMID 28969074, 2017). "In the following step, we checked the expression levels of these three miRNA candidates in eight breast cancer cell lines and compared their expression tendency with TUSC8 and MYLIP in the same breast cancer cell lines." (PMID 32039833, 2020). "Thus, we reported that a novel regulatory pathway composed of TUSC8/miR-190b-5p/ MYLIP was involved in the progression of breast cancer, providing us novel insights and avenues for searching potential biomarkers and therapeutic targets for breast cancer diagnosis and treatment." (PMID 32039833, 2020). "In this study, we validated that MYLIP was a direct target of miR-190b-5p in breast cancer cells and TUSC8 inhibited breast cancer metastasis partly through miR-190b-5p/MYLIP axis." (PMID 32039833, 2020). "In order to further verify that MYLIP is a direct target of miR-19b, we used the MCF7 and MDA-MB-231 breast cancer cell lines as models." (PMID 28969074, 2017). "Furthermore, the lncRNA tumor suppressor candidate 8 (TUSC8) can inhibit the evolution of papillary thyroid carcinoma via the miR-190b myosin regulatory light chain interacting protein (MYLIP) axis, which in turn can inhibit breast cancer growth and metastasis." (PMID 35174066, 2021).
Hypercholesterolemia (6 papers, 2017 to 2025). An increased concentration of cholesterol in the blood. "The recent studies have indicated that the polymorphism site of MYLIP p.N342S is associated with the response to lipid-lowering therapy and might be a pharmacogenetic marker in patients with familial hypercholesterolemia." (PMID 28969074, 2017).
lung carcinoma (6 papers, 2017 to 2025). "Low levels of NR_028502.1, NR_028505.1, NR_051978.1, NR_136240.1, MAPKAPK3, MYLIP were associated with poor survival in patients with lung cancer." (PMID 28968955, 2017). "MYLIP, identified as a tumor suppressor gene, its high expression effectively inhibited the proliferative, migratory, and invasive capabilities of lung cancer." (PMID 40672387, 2025). "lncRNA SGMS1-AS1 is under-expressed in lung cancer of lung adenocarcinoma cells by targeting Mir-106A-5p /MYLIP axis." (PMID 37370148, 2023). "MYLIP was proved to have a significant inhibitory effect on the proliferation, migration, and invasion of lung cancer cells, suggesting that MYLIP may be a tumor suppressor gene for lung cancer." (PMID 38213729, 2024). "Most genes were up-regulated in systemic sclerosis and down-regulated in lung cancer, except for CTSK and MYLIP." (PMID 33691643, 2021). "Among them, GIMAP7 was the most significantly downregulated in lung cancer, CX3CR1 was the most upregulated and MYLIP was the most downregulated in systemic sclerosis." (PMID 33691643, 2021).
dyslipidemia (5 papers, 2012 to 2024). "In this scenario, and because of a possible pharmacotherapeutic target of dyslipidemia, the main aim of this study was to assess the influence of the MYLIP p.N342S polymorphism on lipid profile in Brazilian individuals." (PMID 22741812, 2012). "So the pharmacologic inhibition of MYLIP activity might become a useful method for the treatment of dyslipidemia." (PMID 28969074, 2017).
type 2 diabetes (4 papers, 2017 to 2024). "Furthermore, CpGs annotated to ABCG1, DHCR24, and MYLIP were common to ischemic heart disease and type 2 diabetes." (PMID 37410739, 2023).
cervical cancer (3 papers, 2021 to 2022). A primary or metastatic malignant neoplasm involving the cervix. "miRNA-802 inhibits the growth and metastatic-related phenotypes of cervical cancer cell through targeting MYLIP." (PMID 34988221, 2021).
coronary artery disease (3 papers, 2015 to 2023). "Genetic colocalisation analyses provided weak evidence for a shared causal variant underlying methylation at cg00857282 (MYLIP) and risk of ischemic heart disease (PP = 63%)." (PMID 37410739, 2023).
Obesity (3 papers, 2012 to 2023). Accumulation of substantial excess body fat. "Here we report a 6p deletion of about 1 Mb encompassing five genes (ATXN1, DTNBP1, JARID2, MYLIP and GMPR), identified in a patient with severe ID, hypotonia, brain anomalies, EEG abnormalities, macrosomia, obesity, and ASDs with associated hyperactivity and behavioral abnormalities." (PMID 23324214, 2013). "The SNPs of ABCA-1 (LDL-C and ApoA1/ApoB); LIPC (TC, LDL-C, ApoA1 and ApoB); LIPG (ApoB); MTHFR (TC, TG and LDL-C); MYLIP (TC and TG); PCSK9 (TG, HDL-C, ApoB and ApoA1/ApoB); PPARD (TG and ApoA1/ApoB); and SCARB1 (TG, ApoA1 and ApoB) interacted with overweight/obesity to modulate serum lipid levels." (PMID 23039238, 2012).
prostate carcinoma (3 papers, 2018 to 2025). A carcinoma that arises from epithelial cells of the prostate gland. "In prostate cancer, it enhances tumor progression by stabilizing androgen receptors through MYLIP interaction, and in non-small-cell lung cancer, it contributes to chemoresistance and metastasis through NF-κB and AKT/GSK3β signaling." (PMID 40001982, 2025). "The research conducted in prostate cancer (PC) suggested that CNPY2 promoted cell growth of PC cells by inhibition of androgen receptor (AR) protein degradation through MYLIP-mediated AR ubiquitination." (PMID 32039833, 2020). "In this study, we showed that MYLIP is a novel E3 ubiquitin ligase that recognizes the AR as its target protein in prostate cancer cells." (PMID 29707137, 2018). "The results of these assays showed that AR and MYLIP physically interacted in prostate cancer cells." (PMID 29707137, 2018). "MYLIP could be a viable therapeutic target in diseases like prostate cancer, where CNPY2 is involved." (PMID 40001982, 2025). "To examine whether MYLIP interacts with AR in prostate cancer cells, we first performed immunoprecipitation assay using LNCaP cells transfected with flag-tagged MYLIP." (PMID 29707137, 2018). "In prostate cancer, CNPY2 promotes tumor growth by interacting with MYLIP, preventing the ubiquitination and degradation of androgen receptors (ARs) through the ubiquitin–proteasome pathway." (PMID 40001982, 2025). "Finally, to investigate whether CNPY2 inhibited MYLIP-mediated AR degradation in prostate cancer cells, AR protein levels were examined by immunoblotting of lysates from either CNPY2 or MYLIP knockdown LNCaP cells." (PMID 29707137, 2018).
head and neck cancer (1 paper, 2024). A primary or metastatic malignant neoplasm affecting the head and neck. "We then hypothesised that the 5 upregulated genes (namely, ATPase phospholipid transporting 8A1 [ATP8A1], BAHD1, cathepsin [CTSD], janus kinase 1 [JAK1], and myosin regulatory light chain interacting protein [MYLIP]) play a role in radioresistance of prostate and head and neck cancers." (PMID 39719436, 2024).
Insulin resistance (1 paper, 2023). Increased resistance towards insulin, that is, diminished effectiveness of insulin in reducing blood glucose levels. "Insulin resistance is associated with dysregulation of lipid metabolism and cellular cholesterol homeostasis, and improvement in insulin resistance caused by weight loss in obese individuals was associated with changes in ABCA1 and IDOL/MYLIP in monocytes." (PMID 37094639, 2023).
male infertility (1 paper, 2022). The inability of the male to effect fertilization of an ovum after a specified period of unprotected intercourse. "Among the other validated hits were proteins involved in the ubiquitin proteasome system (STAMBP and MYLIP), transcription (MTA1, PKNOX2), translation (EIF4E3), male infertility (RABL2A, DAZAP1), and virus-induced oncogenesis (MTA1)." (PMID 35452674, 2022).
pancreatic cancer (1 paper, 2022).
Parkinson disease (1 paper, 2023). A progressive degenerative disorder of the central nervous system characterized by loss of dopamine producing neurons in the substantia nigra and the presence of Lewy bodies in the substantia nigra and locus coeruleus. "MYLIP is not considered to be associated with DJ‐1, oxidative stress, or Parkinson's disease." (PMID 37101349, 2023).
prediabetes (1 paper, 2024). "Expression of the 3 LXR target genes, ABCG1, ABCA1, and MYLIP, was inversely associated with risk of prediabetes/T2D, with ABCG1 associations (HR, 1.33 per 1-SD decrease; 95% CI, 1.14–1.56; P = 3.63 × 10–4 in the full model) being similar to that of MYLIP." (PMID 38747290, 2024). "There appeared to be a graded inverse association between increasing tertiles of ABCG1 and MYLIP expression and the risk of incident prediabetes/T2D in both the Initial and the Replication Study." (PMID 38747290, 2024). "Our data showed that, in addition to coexpressed ABCG1, ABCA1, and MYLIP, expression of NR1H2 (encoding LXRβ) itself was also inversely associated with incident prediabetes/T2D, suggesting, for the first time to our knowledge, that dysregulated LAAMP is a major risk factor for T2D." (PMID 38747290, 2024). "During a median 6-year follow-up, lower expression of 3 highly correlated LXR target genes — ABCG1 and ABCA1 (cholesterol efflux) and MYLIP (cholesterol uptake suppression) — and not other CMTN genes, was significantly associated with higher risk of incident prediabetes/T2D." (PMID 38747290, 2024).
uveitis (1 paper, 2025). An inflammatory process affecting a part of or the entire uvea. "For instance, in the uveitis only group, the genes KLHL21, MYLIP, ZNFX1, PDE4A, TNFRSF21, and N4BP2L2 were downregulated, while METTL72, GAPT, CD180, CCR2, and TLR7 were upregulated when comparing uveitis patients with healthy controls." (PMID 40270958, 2025). "Furthermore, there was a significant correlation between patients’ age-specific regulation of genes MYLIP and PDE4A in the uveitis only group and CCR7, LBH, and LCK in the systemic disease-associated uveitis group." (PMID 40270958, 2025).